IL6 (interleukin 6)
Diseases named in the same sentence as IL6 in open-access papers (continued):
Sharing a sentence is not in itself a finding about the gene and the disease.
COVID-19 (continued). "Dyshemostasis characterized COVID-19, with increased prothrombin time, low platelet count, and high levels of interleukin 6, fibrinogens, and von Willebrand factor, among other abnormalities." (PMID 36527584, 2023). "We found significantly higher serum levels of IL-6, IL-8, and IL-10 in patients with severe COVID-19 and in those with a fatal outcome." (PMID 37969879, 2023). "Previous studies have shown the clinical benefit of administration of certain cytokine inhibitors, including anakinra (IL-1 inhibitor) and tocilizumab (IL-6 inhibitor), in patients with severe COVID-19." (PMID 36651846, 2023). "Another meta-analysis found a link between IL-6 levels and severity, indicating that the IL-6 level was a perfect predictor of poor prognosis in COVID-19." (PMID 37124230, 2023). "In this prospective observational study, we demonstrated that IL-6, PCT, and CRP were equally able to identify patients at low risk for severe COVID-19 progression already at hospital admission." (PMID 37937220, 2023). "Another potential COVID-19 therapeutic target, tocilizumab, has the ability to bind IL-6R, therefore blocking the downstream effects of IL6 over-induction." (PMID 37043472, 2023). "As a logical consequence, IL-6 signaling inhibition was postulated as a potential tool for reducing the inflammatory burden of COVID-19, as earlier studies observed an improvement in the clinical status of patients." (PMID 37818368, 2023). "Several of these cytokines, including IL-6, have been found to be overexpressed and positively correlated with disease severity in COVID-19 patients." (PMID 36992700, 2023). "Tocilizumab is an IL6 receptor blocker that effectively blocks the IL6 signal transduction pathway and is an effective therapeutic drug for COVID-19 patients." (PMID 37564653, 2023). "Data from alternative studies have shown the prognostic importance of IL-6 levels in COVID-19 but a direct comparison between the MSD and Roche assays are lacking." (PMID 37650680, 2023). "Anti-N antibody plays a crucial role in the pathogenesis of severe COVID-19 cases through the enhancement of IL-6 production from macrophages in the presence of the N protein." (PMID 37896795, 2023). "For example, there are many clinical reports describing elevated cytokines, particularly IL-6, in patients with severe COVID-19." (PMID 37515150, 2023). "Nevertheless, the sample size of that study is too small to refute the general belief that IL-6 is a prognostic biomarker for COVID-19." (PMID 36573520, 2023). "Similar reduction in concentration of multiple cytokines, including IL-6, in COVID-19 patients from the second versus the first wave in Italy were also reported." (PMID 36817433, 2023). "The current study aimed to evaluate the use of IL-1 antagonist anakinra and IL-6 antagonist tocilizumab as well as corticosteroids in controlling mild or moderate COVID-19 cases." (PMID 37046952, 2023). "Many inflammatory markers such as neutrophil-lymphocyte ratio (NLR), D-dimer, serum ferritin, C-reactive protein (CRP), and interleukin-6 (IL-6) were used for the diagnosis and prognosis of COVID-19." (PMID 37575788, 2023). "Components of the COVID-19 cytokine storm (IL-6, TNF-α, and IL-1) have been implied to stimulate ATX expression and/or activity in various cell types and vice versa, LPA has been reported to stimulate TNF and IL-6 expression in various contexts." (PMID 36851766, 2023). "In the prospective, longitudinal cohort study, excessive production of IL-1β, IL-6, IL-8, transforming growth factor-β, interferon-α, and interferon-γ was observed in the semen of patients with COVID-19 during a 60-day research period." (PMID 37958725, 2023). "Analyses of hospitalized severe COVID-19 patients in other studies have also identified IL-6, IL-10, CCL20, and miR-451a as key factors closely related to COVID-19 mortality." (PMID 38140218, 2023).
COVID-19 (continued). "Elevated levels of IL-6 not only correlate with morbidity and mortality in COVID-19 patients but are a druggable target." (PMID 37834869, 2023). "Previous studies in critically ill patients with COVID-19 living at high altitude showed that interleukin-6 (IL-6) together with the neutrophil/lymphocyte ratio (NLR) and lactate dehydrogenase (LDH) were independent predictors of mortality." (PMID 36675573, 2023). "IL-6 is known to be involved in the inflammatory response, and elevated levels of IL-6 have been observed in some COVID-19 patients." (PMID 38248752, 2023). "We analysed the serial MPO, ADA, CCL22, TNFα, and IL-6 mRNA expression in nasopharyngeal specimens of 154 COVID-19 and 163 control hospitalized patients in the fifth wave of COVID-19 in Hong Kong." (PMID 36482706, 2023). "We designed a systematic review and meta-analysis to assess the relationship between IL-6 levels and long COVID-19." (PMID 37095536, 2023). "According to the New Coronavirus Pneumonia Prevention and Control Program (7th edition), a decreasing level of IL-6 indicates aggravation of COVID-19." (PMID 37095536, 2023). "Depressed ApoA1 protein levels in COVID-19 patients are negatively correlated with C-reactive proteins, IL-6, d-dimers, prothrombin time and thrombin time." (PMID 37587394, 2023). "Sarilumab and siltuximab, as well as tocilizumab, are Food and Drug Administration (FDA)-approved IL-6 inhibitors that can be used by patients with COVID-19." (PMID 36674700, 2023). "In these situations, we examined the prognostic value of four biomarkers (IFN-λ3, TARC, IL-6, and CP) for COVID-19." (PMID 36996138, 2023). "For example, in a retrospective single-center study conducted on 728 patients with COVID-19, the prognostic significance of elevated IL-6 levels for assessing mortality and a severe disease course was studied." (PMID 36982611, 2023). "Hypertensive COVID-19 patients from both infection waves had significantly higher serum concentration of IL-6, TNF, IP-10, IL-29, IL-8, IL-12p70, IFN-α2, IFN-β, IL-10 and IFN-γ in comparison with controls." (PMID 36817433, 2023). "IL-1 and IL-6 are two key proinflammatory cytokines that are involved in the immune response to COVID-19." (PMID 37046952, 2023). "This drug works by blocking interleukin-6 (IL-6), an inflammatory protein involved in the exaggerated immune response that can lead to severe complications in COVID-19 patients." (PMID 37512147, 2023). "In severe cases, through inflammatory mediators like IFN-α, IL-1β, IL-6, CCL2, CCL5 and others, COVID-19 causes an inflammatory process that if uncontrolled evolves into lung tissue injuries, systemic inflammations and pathogenesis, and organ failure." (PMID 37662953, 2023). "Currently, available evidence overall argues the COVID-19 in the severe state exhibits a cytokine storm with elevated plasma levels IL-1, and IL-6." (PMID 37692307, 2023). "By impeding the cytotoxicity of immune cells in serious COVID-19 cases, IL-6 adds to the seriousness of the illness and the related issues." (PMID 37958192, 2023). "IL-6, playing a key role in the pathogenesis of COVID-19, becomes a target for therapeutic interventions (research on tocilizumab and other IL-6 antagonists is underway)." (PMID 37686271, 2023). "NACE2i also reduced IL-6 expression and increased perforin expression in PBMCs isolated from a patient with severe COVID-19." (PMID 37369668, 2023). "The elevated levels of IL-6, D-dimers, CRP, neutrophils, and a low lymphocyte count have been associated with severe forms of COVID-19." (PMID 38203482, 2023). "Because an elevation of IL-6 has been identified in severe cases of COVID-19, monoclonal antibodies that block IL-6 receptor signaling, such as tocilizumab, have been tested." (PMID 37631998, 2023). "This study reported the mortality rate of COVID-19 in children was 28.52% and all of them reported with increasing IL-6 levels." (PMID 37889917, 2023).
COVID-19 (continued). "Deceased or IOT COVID-19 patients had statistically increased levels of Dimer-D, IL-6, and KL-6 (p = 0.007, p = 0.048, p < 0.001, respectively)." (PMID 36674646, 2023). "Tocilizumab is a recombinant humanized IgG1 monoclonal antibody that reduces the pro-inflammatory effect of IL-6 and has previously been shown to reduce mortality and the need for mechanical ventilation in COVID-19 patients." (PMID 37400927, 2023). "High plasma levels of SARS-CoV-2 induce the elevation of cytokines such as IL-6 and enhance severe COVID-19 progression." (PMID 38094124, 2023). "By detecting the levels of IL-6, it is possible to identify the success rate of COVID-19 vaccination." (PMID 38813035, 2023). "The results of a recent multicenter clinical trial showed that the use of evolocumab reduces the 30-day mortality rate or intubation requirement in severe COVID-19 patients by 30%, accompanied by a significant reduction in serum IL-6 levels." (PMID 38093957, 2023). "A similar cytokine profile of IFN-γ, TNF-α, IL-2, IL-6, IL-10, IL-1β, and GM-CSF was also observed in COVID-19 patients." (PMID 38143441, 2023). "Another large retrospective cohort study found that IL-6 levels were correlated with mortality in patients with COVID-19." (PMID 37161412, 2023). "Elevated levels of plasma IL-1β, IL-6, and TNF were shown to be associated with postacute sequelae of COVID-19." (PMID 37228441, 2023). "In severe/critical COVID-19 patients, IL-6, CRP, NLR, PLR, glucose, AST, urea, creatinine, and eGFR were significantly higher compared with the reference interval, while eosinophil count was significantly lower." (PMID 36838284, 2023). "In our study, the elevation of IL-6 and IL-10 was observed in newborns of mothers with COVID-19, who were born inflamed and possibly with a cytokine storm, as mentioned." (PMID 36979888, 2023). "Under our experimental conditions, instead, IL-6, despite its well-recognized correlation with COVID-19 severity, was completely ineffective, excluding the role of this cytokine in NOS2 induction." (PMID 37893073, 2023). "of 140 COVID-19 patients reports a 67.9% and 65% rise in IL-6 and CRP protein levels in serum, which corresponding to the severity of the disease." (PMID 37649125, 2023). "These inflammasome derivatives are correlated with COVID-19 severity markers such as IL-6, CRP and LDH." (PMID 36961847, 2023). "During a cytokine storm, IL-6 levels are significantly increased in the serum of COVID-19 patients with severe disease." (PMID 37109231, 2023). "In particular, clinical trials based on IL-6 signaling pathway intervention are underway for COVID-19 treatment." (PMID 37896755, 2023). "Severe COVID-19 cases are characterized by an increase in pro-inflammatory cytokines plasma levels, especially interleukins IL-1β, IL-2, IL-6, IL-7, and IL-10 granulocyte-macrophage colony-stimulating factor (GM-CSF) and tumor necrosis factor-alpha (TNF-a)." (PMID 37445296, 2023). "Various existing medications can block the IL-6 pathway; however, only tocilizumab (an IL-6 receptor antagonist) has had a reasonable effect in COVID-19." (PMID 38155729, 2023). "Plasma IL-6 concentrations were measured on 191 COVID-19 patients using the Roche Elecsys IL-6 assay and the Meso Scale Discovery assay." (PMID 37650680, 2023). "Compared with healthy controls, a significant number of genes related to inflammation, such as IFN-γ and -α responses and TNFA and IL-6 pathways, were highly enriched in COVID-19 kidneys." (PMID 36749641, 2023). "Survival analysis confirmed the highly significant impact of IL-6 (P = 8.56e−23) on the survival of COVID-19 patients and also identified a nominally significant effect of IL-2R on survival (P = 0.0003)." (PMID 37475855, 2023). "Elevated levels of IL-6 correlate with morbidity and mortality in COVID-19 patients and the antibody tocilizumab, which targets IL-6, improved survival in hospitalized COVID-19 patients with a demand for oxygen therapy and systemic inflammation." (PMID 37834869, 2023).
COVID-19 (continued). "C-reactive protein (CRP) and interleukin-6 (Il-6) levels correlate positively with COVID-19 severity and mortality." (PMID 37373613, 2023). "According to high-sensitivity troponin (hsTnI) levels, patients with COVID-19 were divided into high- and low-sensitivity groups, and interleukin 6 (IL6) expression and lymphocyte subsets were compared." (PMID 37564653, 2023). "High levels of serum IL-6 were observed in patients with severe and critical COVID-19 in comparison to asymptomatic patients, and the highest values were observed in non-survivors." (PMID 37685739, 2023). "A visual inspection of the IL-6 trends shows that in patients who died from COVID-19 complications, IL-6 levels continued to rise during the first two week of illness and remained elevated until the third week." (PMID 38138084, 2023). "The overexpression of CRP, ferritin, LDH, TNF-α, IL-1β, IL-6, IL-2, IFN-γ, and vascular endothelial growth factor (VEGF) can be associated with COVID-19 severity." (PMID 37654571, 2023). "Hospitalized COVID-19 patients with hyperglycemia have higher levels of interleukin-6 (IL-6) and D-dimers." (PMID 36741600, 2023). "The effect estimates on sepsis were similar in magnitude to those seen in severe COVID-19 (OR 0.69, 95% CI 0.57 to 0.84), where IL-6 blockade is currently recommended." (PMID 36716318, 2023). "Serum adiponectin levels significantly and positively correlated with IL-6, ceramides, and glycerophospholipids serum levels during COVID-19." (PMID 37408184, 2023). "In our study, the detection range of the mSAMs-GA-Apt FET sensor covered the concentration of IL-6 used to distinguish the patients with severe COVID-19." (PMID 36679421, 2023). "The median serum IL-6 in the mild COVID-19 group was significantly lower (3.59 pg/mL [min–max of 1.50–638.30]) than that of the severe COVID-19 (28.82 pg/mL [min–max of 5.52–926.30], P <0.005)." (PMID 38099004, 2023). "While much has been discovered, for instance, the critical role of IL-6, there are aspects of severe COVID-19 that require further research." (PMID 38069327, 2023). "Another systematic review of 147 studies showed that COVID-19 patients who eventually died had 42.1-fold higher mean IL-6 concentrations than patients who survived." (PMID 38203482, 2023). "Monoclonal antibodies against interleukin 6 (IL-6) like tocilizumab are recommended to treat COVID-19 patients requiring HFNO or mechanical ventilation because of its clear mortality benefits." (PMID 37745269, 2023). "Increased cytokine levels in COVID-19 including IL-1β, IL-6, interferon-inducible protein 10 (IP-10), TNF-alpha, IFN-γ, macrophage inflammatory protein (MIP) 1α and 1β, and vascular endothelial growth factor (VEGF) were observed." (PMID 37753372, 2023). "Oher studies investigating immune features of COVID-19 convalescent trends observed elevated levels of IL-6 and IL-1β in individuals with PASC." (PMID 37077911, 2023). "In one study of 52 individuals infected with COVID-19, the maximum concentrations of plasma cytokines (IL-2, IL-5, IL-17, IL-8, IL-10, IL-6, IL-12p70, and IFN-γ) were found to be significantly higher in those who had died than in those who had survived." (PMID 36766961, 2023). "Interleukin-6 is a well-established fever-generating molecule in inflammation and is known to be upregulated in COVID-19 patients." (PMID 37587219, 2023). "A meta-analysis deserves attention, in which prognostic factors and the significance of elevated IL-6 levels in this pathology were determined in 1426 patients infected with COVID-19." (PMID 36982611, 2023). "Higher levels of IL-6 and TNF-α were associated with disease severity in COVID-19 patients and significant predictors of mortality and survival." (PMID 38057707, 2023). "The IL-6 inhibitors investigated for COVID-19 include tocilizumab and sarilumab, which have been administered IV as single doses of 8 mg/kg (up to 800 mg) and 400 mg, respectively." (PMID 37368815, 2023).
COVID-19 (continued). "Although previous studies have shown that patients with COVID-19 residing in high-altitude tend to have higher levels of inflammatory cytokines, particularly IL-6, IL-10 and TNF-α." (PMID 37264338, 2023). "Chen and colleagues reported that in severe cases of COVID-19, there were higher levels of IL-6 and TNF-α than in mild cases." (PMID 37363608, 2023). "A study examined the immunological responses of 13 COVID-19 patients and observed that the illness has elevated cytokines proportion with IL-6, IL-10, and TNF-alpha, along with enhanced monocytes and neutrophil counts." (PMID 37754237, 2023). "Multiple studies including meta-analyses have confirmed the relationship between COVID-19, disease severity, and IL-6 levels." (PMID 36987476, 2023). "Patients with severe COVID-19 and with IL-6 values at 24 h ≥ 11, NLR values at 24 h ≥ 22, and NLR values at 72 h ≥ 14 were 8.3, 3.8, and 3.8 times more likely to die at 28 days, respectively." (PMID 36675573, 2023). "The levels of IL-1, IL-6 and TNF-α were positively associated with increased risk of arrhythmia in COVID-19 patients." (PMID 37251383, 2023). "The pooled estimate of IL-6 in the long COVID-19 population from the included studies revealed a mean value of 20.92 pg/ml (95% CI = 9.30–32.54 pg/ml, I2 = 100%, P < 0.01), which was validated by the sensitivity analysis." (PMID 37095536, 2023). "Another systematic review of 147 studies has shown that deceased COVID-19 patients had 42.1 times higher mean concentrations of IL-6 than patients that survived." (PMID 36983566, 2023). "Among inflammatory cytokines, IL-6 is dramatically increased in COVID-19 patients and it has been reported that more than half of admitted patients in the emergency unit showed elevated IL-6 levels." (PMID 37297598, 2023). "Specific biomarkers associated with severe COVID-19 illness in cancer patients include C-reactive protein (CRP) and interleukin (IL)-6." (PMID 36673615, 2023). "In the current study, the most significant change in the EVs’ cytokine cargo was related to the IL-6 content in the EVs of COVID-19 patients with severe disease." (PMID 36982991, 2023). "This animal model study corroborates the observations in humans, indicating that COVID-19 can induce an increase in the number and activity of monocytes in the peripheral tissues, and these effects can be attenuated by inhibiting the IL-6 pathway." (PMID 38090572, 2023). "This trend, alongside correlations with severe organ injuries and elevated levels of pro-inflammatory cytokines like IL-6, underscores the importance of serum calcium in the pathophysiological mechanisms of COVID-19." (PMID 38203589, 2023). "An elevated level of IL-6 in COVID-19 was correlated with disease severity and mortality and used as a tool for disease prognosis and clinical profile." (PMID 37243203, 2023). "Imbalanced ACE/ACE2 and RAAS activation are responsible, at least in part, for COVID-19 progression which can lead to cardiac damage by inducing a hyperinflammatory response characterized by high levels of IL-6, IL-1, and TNF-α." (PMID 37226245, 2023). "Given the near ubiquitous identification of IL-6 as a powerful predictor of disease course in initial studies, along with its involvement in other disorders of cytokine storms, IL-6 and its signaling pathways became logical targets in severe COVID-19." (PMID 37427016, 2023). "IL-6 levels together with ACE-2 rs2285666 and IFITM-3 rs12252 genetic variants were suggested here as significant predictors for COVID-19 fatality." (PMID 38155729, 2023). "The blood concentrations of the antiviral cytokine IFN-α and proinflammatory cytokines TNF, IFN-γ, IL-6, IL-8, IL-17, and IL-33 were significantly increased in COVID-19 patients both at admission and one week later, compared to healthy controls." (PMID 37174682, 2023).